TF (transferrin)
Diseases named in the same sentence as TF in open-access papers (continued):
Sharing a sentence is not in itself a finding about the gene and the disease.
Candida infection (3 papers, 2013 to 2025). "Also, C. albicans infection has been shown to stimulate hepcidin production in the liver and cause a decrease in serum transferrin levels in the murine model of disseminated Candida infection." (PMID 24146619, 2013). "Functional validation using the established Drosophila model of Candida infection indicated virulence defects in all three TF knockout mutants compared to wild type (WT), with sef1Δ mutant exhibiting significant attenuation." (PMID 41476647, 2025).
co-infection (3 papers, 2018 to 2023). "In the present study, significant upregulation of IL-1β, transferrin, and C3 gene expression was observed post-turmeric oil treatment in P. hypophthalmus with co-infection conditions." (PMID 36119096, 2022). "The firefly luciferase activity was significantly higher than that of the control group after co-infection of pGreenII62-SK::TcbHLH14/pGreenII0800-LUC::pTcAOC/TcGLIP into N. benthamiana leaves, indicating that the TF TcbHLH14 could activate the transcription of TcAOC and TcGLIP gene promoters." (PMID 37108541, 2023).
colorectal adenoma (3 papers, 2014 to 2023). An adenoma that arises from the colon or rectum. "In the present study, we analyzed the TF expression dynamics throughout the mucosa-adenoma-tumor stages using GEO microarray data collected from patients with concurrent colorectal adenomas and tumors, including adjacent mucosae." (PMID 34094897, 2021). "To extract meaningful biological information from this list, we initially focused on the TF genes displaying the most markedly upregulated expression in colorectal adenomas together with the lowest publication scores." (PMID 24472434, 2014). "We pinpointed the TF genes whose expression is significantly altered in colorectal adenomas and characterized the extent and direction of these changes." (PMID 24472434, 2014). "For this reason, we attempted in the present study to comprehensively characterize the TF gene expression changes that occur in colorectal adenomas." (PMID 24472434, 2014). "The transcription-regulating network of colorectal adenomas (compared with that of normal colorectal mucosa) is characterized by significantly altered expression of over 250 TF genes, many of which have never been investigated in relation to colorectal tumorigenesis." (PMID 24472434, 2014).
Crohn disease (3 papers, 2017 to 2024). A gastrointestinal disorder characterized by chronic inflammation involving all layers of the intestinal wall, noncaseating granulomas affecting the intestinal wall and regional lymph nodes, and transmural fibrosis. "•MDA, PON-1, CAT, albumin, transferrin, and TAC indicate Crohn's disease flares." (PMID 39368456, 2024).
cyst (3 papers, 2021 to 2023). A sac-like closed membranous structure that may be empty or contain fluid or amorphous material. "After isolation of antigen B from sterile cyst fluid, the rats were randomly divided into four groups: saline, EAE, EAE + teriflunomide (EAE + TF), and EAE + antigen B (EAE + AngB)." (PMID 36582052, 2023).
cystic fibrosis (3 papers, 2017 to 2023). Autosomal recessive disorder caused by pathogenic variants in the CFTR gene (cystic fibrosis transmembrane conductance regulator), which encodes a chloride and bicarbonate channel expressed in epithelial cells, and follow the diagnosis criteria. "In human air ways, iron is mostly found in the form of bound to transferrin, lactoferrin, and ferritin which are iron binding proteins and the concentration of free iron is completely low, about 8 μM in sputum of cystic fibrosis patients." (PMID 37475017, 2023). "The aim of this study was to evaluate the serum hepcidin levels against the selected parameters of iron status (ferritin, transferrin, and serum iron levels) in children with cystic fibrosis and healthy controls." (PMID 30057485, 2018).
eczema (3 papers, 2019 to 2025). "We found that lower serum iron remained associated with greater DLQI impairment after adjustment for other covariates, while higher transferrin levels correlated with more severe eczema scores (EASI and SCORAD)." (PMID 41374035, 2025).
endotoxemia (3 papers, 2015 to 2019). "Injection of low doses of LPS in healthy volunteers induced endotoxemia and TF mRNA had a 125-fold increase in whole blood cells." (PMID 31139194, 2019). "Although only pups from the CF group showed elevated serum endotoxemia in a previous study, in this study, the 21-d-old offspring of the TF group presented with higher p-NFκB p65 protein levels in the liver and an increased serum concentration of TNF-α." (PMID 26147005, 2015).
Ewing sarcoma (3 papers, 2016 to 2025). A small round cell tumor that lacks morphologic, immunohistochemical, and electron microscopic evidence of neuroectodermal differentiation. "TRIM8 also ubiquitinates and degrades EWS/FLI, a driver fusion-TF in Ewing sarcoma." (PMID 41184227, 2025). "Notably, the addition of holo-transferrin, a source of biologically available iron, to the cell culture media significantly rescued the toxicity of ciclopirox toward Ewing sarcoma cells, demonstrating that iron is a target of ciclopirox." (PMID 27557498, 2016).
ferroportin disease (3 papers, 2010 to 2023). "SLC40A1 dysfunction causes ferroportin disease, and autosomal dominant iron overload disorder characterized by cellular iron retention, principally in reticuloendothelial cells, correlating with high serum ferritin and low to normal transferrin saturation." (PMID 40225168, 2023). "Transferrin saturation is low to normal in classical ferroportin disease and increased in patients with the non-classical phenotype." (PMID 20691492, 2010).
glomerulosclerosis (3 papers, 2012 to 2017). A hardening of the kidney glomerulus caused by scarring of the blood vessels. "Urinary transferrin and 24-h proteinuria were independent factors associated with the development of glomerulosclerosis." (PMID 22607047, 2012). "Urinary transferrin and 24-h proteinuria were independent factors associated with severe glomerulosclerosis defined as ≥ 10 % glomeruli showing segmental adhesions or sclerosis." (PMID 22607047, 2012). "Severe glomerulosclerosis was significantly predicted by urinary transferrin (AUC = 0.82, p = 0.007) and 24-h proteinuria (AUC = 0.79, p = 0.014)." (PMID 22607047, 2012). "In our study, urinary transferrin has an increased predictive value relative to other urinary proteins as assessed by AUC, predicting the severity of mesangial cellularity and glomerulosclerosis in children with MesPGN." (PMID 22607047, 2012). "The optimal cut-off value for urinary transferrin to predict severe glomerulosclerosis was 136 mg/g uCr (sensitivity 100 %, specificity 74 %)." (PMID 22607047, 2012). "Other studies have found that urinary TF may predict the severity of mesangial cellularity and glomerulosclerosis in the early stages of glomerular diseases." (PMID 28158993, 2017). "Urinary transferrin achieved the area under-the-receiver-operating-characteristic curve (AUC) of 0.86 and 0.82, respectively, for predicting severe mesangial cellularity and glomerulosclerosis." (PMID 22607047, 2012). "Our result indicates that urinary transferrin may predict the severity of mesangial cellularity and glomerulosclerosis in the early stages of potentially progressive glomerular diseases." (PMID 22607047, 2012). "Urinary transferrin could, as an independent factor, predict severe mesangial cellularity and glomerulosclerosis." (PMID 22607047, 2012).
hemosiderosis (3 papers, 2019 to 2022). Accumulation of iron in internal organs. "We detected a significant correlation between hemosiderosis of the pancreas and heart, which is more likely due to the same L-type calcium iron channels in the two organs, taking up circulating non-transferrin-bound iron." (PMID 34884261, 2021).
Hypercholesterolemia (3 papers, 2021 to 2024). An increased concentration of cholesterol in the blood. "In such case, the identification of A2AR and Flotillin-1 downregulation and transferrin and ferritin alterations might represent a novel panel of very early predictive biomarkers of the cardiovascular risk in hypercholesterolemia." (PMID 38534331, 2024). "CCDC115-CDG patients present with CDG-II type serum transferrin profile related to hepatosplenomegaly, neurological affectations, elevated serum ALT and ALP levels, mild hypercholesterolemia, low serum Cp, and Wilson-like copper disturbances." (PMID 34572285, 2021). "They present CDG-II type serum transferrin profile related to steatosis, elevated serum levels of ALT and ALP, hypercholesterolemia, low serum Cp and slightly alterations of copper metabolism; they do not develop hepatosplenomegaly or neuropsychiatric disturbances." (PMID 34572285, 2021).
hyperphosphatemia (3 papers, 2015 to 2023). Abnormally high level of phosphate in the blood. "Multivariate linear regression revealed that hyperphosphatemia was associated with elevations in the transferrin and serum albumin levels and normalized protein catabolic rate (nPCR) and reductions in the hemoglobin level, residual Ccr, and PD Ccr." (PMID 26187601, 2015). "Similar to these studies, we found that hyperphosphatemia was positively associated with nPCR and the albumin and transferrin levels and negatively associated with age and PD adequacy." (PMID 26187601, 2015). "Other factors found to be independently associated with hyperphosphatemia were elevations in the transferrin (p = 0.007) and serum albumin levels (p = 0.049) and nPCR (p < 0.001) and decreases in the hemoglobin level (p = 0.015), residual Ccr (p < 0.001), and PD Ccr (p < 0.001)." (PMID 26187601, 2015).
hyperuricemia (3 papers, 2022 to 2024). An abnormally high level of uric acid. "A nationwide population study conducted in China demonstrated that levels of serum ferritin (SF), transferrin, and soluble transferrin receptor (sTfR) are positively associated with the risk of hyperuricemia." (PMID 39022306, 2024). "In a study on the association between markers of iron status and the risk of hyperuricemia in Chinese adults, the researchers found a positive correlation between serum ferritin, transferrin and hyperuricemia." (PMID 39712490, 2024).
hypophosphatemia (3 papers, 2014 to 2026). Lower than normal levels of phosphates in the circulating blood. "Over 4-8 weeks, ferric carboxymaltose more consistently increased iron stores (ferritin/transferrin saturation) compared with the alternatives at the cost of a higher risk of hypophosphatemia." (PMID 41921282, 2026). "In addition to overall estimates, results are presented by predefined timepoints (4, 8, 12 and 24 weeks) for hemoglobin, ferritin, transferrin saturation, serious adverse events, and hypophosphatemia." (PMID 41921282, 2026).
influenza (3 papers, 2012 to 2025). An acute viral infection of the respiratory tract, occurring in isolated cases, in epidemics, or in pandemics; it is caused by serologically different strains of viruses (influenzaviruses) designated A, B, and C, has a 3-day incubation period, and usually lasts for 3 to 10 days. "To confirm that CWE had an anti-influenza effect, we performed an endocytosis inhibition assay using transferrin, a specific marker for clathrin-mediated endocytosis." (PMID 40577311, 2025). "These selected proteins, such as plasma protease C1 inhibitor, hemopexin, transferrin, complement factor B and complement C3, have been identified as candidate biomarkers of acute respiratory virus infection or exhibited obvious fold changes during influenza infection." (PMID 34867309, 2021).
intracerebral hemorrhage (3 papers, 2016 to 2022). A cerebrovascular disorder characterized by bleeding into one or both cerebral hemispheres including the basal ganglia and the cerebral cortex. "Another study performed in patients with intracerebral hemorrhage also demonstrated that serum ferritin at baseline was markedly higher and iron as well as transferrin was lower in patients with poor outcome (mRS ≥ 3) at 90 days." (PMID 30451393, 2018).
juvenile idiopathic arthritis (3 papers, 2018 to 2022). Juvenile idiopathic arthritis (JIA) is the term used to describe a group of inflammatory articular disorders of unknown cause that begin before the age of 16 and last over 6 weeks. "Therefore, the objective of this study was to evaluate the serum glycosylation profile of transferrin isoforms in juvenile idiopathic arthritis and to assess the potential diagnostic utility of the marker in JIA." (PMID 29761223, 2018). "In the present study, the glycosylation profile of transferrin isoforms was determined in a spectrum of juvenile idiopathic arthritis, using the capillary electrophoresis technology." (PMID 29761223, 2018). "To summarize, this pilot study shows a specific profile of transferrin isoforms in patients with juvenile idiopathic arthritis." (PMID 29761223, 2018). "The aim of this study was to assess the effect of juvenile idiopathic arthritis (JIA) on the serum glycosylation profile of transferrin isoforms." (PMID 29761223, 2018). "Serum TfR has previously been observed to be elevated in children with juvenile chronic arthritis, without any correlation to serum transferrin or ferritin levels, indicating that serum TfR is an inadequate indicator of iron levels in the presence of chronic inflammation." (PMID 31687055, 2019).
keratoconus (3 papers, 2013 to 2021). A degenerative, structural disorder of the eye, characterized by a cone-shaped protrusion of the cornea. "The g.3296G>A, g.3481A>G, c.–2G>A and polymorphisms of the TF gene may modulate the risk of keratoconus, by its involvement in altered iron homoeostasis and oxidative stress induction." (PMID 24350254, 2013).
lipid metabolism disorders (3 papers, 2022 to 2024). "TFC reduces the levels of TG, TF, and FFA by reducing the accumulation of fat around the body, so as to relieve the body’s lipid metabolism disorder and oxidative stress." (PMID 35885412, 2022).
malignant glioma (3 papers, 2011 to 2023). A grade III or grade IV glioma arising from the central nervous system. "Therefore, VEGF is a factor related to increased TF expression or activity in malignant glioma." (PMID 36910644, 2023).
meningococcal infection (3 papers, 2013 to 2025). Infections with bacteria of the species neisseria meningitidis. "One particularly important advance has been the demonstration that transgenic mice expressing the human serum iron transport protein transferrin are susceptible to invasive meningococcal disease because Neisseria sp." (PMID 23935487, 2013). "Furthermore, meningococcal infection has been shown to subvert iron homeostasis in infected cells by interfering with transferrin uptake by infected cells, which, consequently, displays a transcriptional profile indicative of iron deficiency following meningococcal infection." (PMID 41477005, 2025). "In this study, we used an experimental meningococcal infection in transgenic mice expressing the human transferrin to show multi-organ infection." (PMID 32977487, 2020). "In this work, we used experimental meningococcal infection in transgenic mice expressing the human transferrin and showed that infection with hypervirulent strains of Nm such as those belonging to the cc11 led to high multi-organ infection in the kidneys, liver, spleen, heart and brain." (PMID 32977487, 2020). "While other models may only insure meningococcal adhesion, the bacterial growth in transgenic mice expressing the human transferrin renders the model reliable for invasive meningococcal infections and enable several applications using several routes of infection (intraperitoneal and intranasal)." (PMID 32977487, 2020).
mental disorder (3 papers, 2012 to 2022). A disease that has its basis in the disruption of mental process. "A higher transferrin, indicative of lower iron status, was also associated with increased risk of gender identity disorders and decreased risk of psychogenic disorder." (PMID 36590208, 2022).
nasopharyngeal carcinoma (3 papers, 2019 to 2023). A carcinoma arising from the nasopharyngeal epithelium. "We found that tongue squamous cell carcinoma and nasopharyngeal carcinoma cells (including CAL33, CNE-2, S18, and S26) have a similar level of both transferrin (TF) and transferrin receptor (TFRC) genes." (PMID 36012290, 2022).
pancreatic ductal adenocarcinoma (3 papers, 2016 to 2021). An infiltrating adenocarcinoma that arises from the epithelial cells of the pancreas. "Pancreatic ductal adenocarcinoma (PDAC) expresses high levels of TF expression, whereas no TF expression was observed in normal pancreatic samples." (PMID 34359742, 2021).
pancreatitis (3 papers, 2017 to 2024). Inflammation of the pancreas. "The aim of this study is to evaluate the effect of pancreatitis on the serum profile of transferrin isoforms." (PMID 35329964, 2022). "As expected, the total transferrin concentration was diminished in both forms of pancreatitis, with an apparent greater decrease in acute pancreatitis." (PMID 35329964, 2022). "First, we found the changed profile of transferrin isoforms in pancreatitis, with more severe changes in acute pancreatitis." (PMID 35329964, 2022). "In this paper, we tried to determine the profile of transferrin isoforms in pancreatitis, in acute as well as in chronic forms of disease, in accordance with the knowledge on the changes of protein glycosylation in the course of inflammatory diseases." (PMID 35329964, 2022).
parasitic infection (3 papers, 2008 to 2025). "Transferrin and hepcidin also play roles in fish immunity; for example, hepcidin has been identified as an antimicrobial peptide, and transferrin expression increases during parasitic infection in carp." (PMID 40150321, 2025). "The regulation of milk-gland protein and transferrin transcription remains to be described, but may similarly be subject to hormonal regulation, which in turn may be influenced by parasite infections." (PMID 18335067, 2008).
polycythemia (3 papers, 2020 to 2021). Abnormally high mass or concentration of red blood cells in the blood, either due to an increase in erythropoiesis or a decrease in plasma volume. "Polycythemia in this setting is thought to be a consequence of elevated transferrin saturation levels, resulting in increased iron uptake by erythroid precursor cells." (PMID 32399341, 2020). "Although the total MPs, PMPs, RMPs, GMPs and EMPs counts were elevated in PV versus secondary polycythemia or healthy subjects (p < 0.001 for all), TF+MPs (which displayed positivity for CD142) concentrations were similar in PV, secondary polycythemia and controls." (PMID 34357048, 2021).
prion disease (3 papers, 2009 to 2025). A transmissible disease that is caused by a protein that is able to induce abnormal folding of normal cellular proteins, leading to characteristic spongiform brain changes, which are associated with neuronal loss without an inflammatory response. "Transferrin regulates iron homeostasis, and abnormal iron homeostasis in prion diseases may contribute to oxidative stress and neurodegeneration." (PMID 41282248, 2025). "In this report, we demonstrate that prion disease–affected human, hamster, and mouse brains show increased total and redox-active Fe (II) iron, and a paradoxical increase in major iron uptake proteins transferrin (Tf) and transferrin receptor (TfR) at the end stage of disease." (PMID 19283067, 2009).
protein-energy malnutrition (3 papers, 2014 to 2019). A nutritional deficit that is caused by inadequate protein or calorie intake. "Low levels of plasma transferrin are found during protein-energy malnutrition." (PMID 31730639, 2019).